GAPDH (glyceraldehyde-3-phosphate dehydrogenase)
Diseases named in the same sentence as GAPDH in open-access papers (continued):
Sharing a sentence is not in itself a finding about the gene and the disease.
dengue (4 papers, 2018 to 2022). "based on our study, we suggest ACTB with HPRT/GAPDH combination for normalization in qPCR for precise quantification of transcripts in dengue infected studies." (PMID 30071880, 2018). "GAPDH was detected by immunofluorescence (red fluorescent) in the cytoplasm and nucleus of the hepatocytes and Kupffer cells in the liver samples from the fatal dengue case and the control." (PMID 30804377, 2019). "Similarly, ACTB has also been widely used in dengue related studies while GAPDH has been used in dengue studies as sole reference gene or with combination of other reference genes." (PMID 30071880, 2018). "GAPDH in platelets were differentially expressed only in ST elevation myocardial infarction and HIV, dengue, and H1N1 (p < 0.05)." (PMID 35770000, 2022). "For example, GAPDH regulates hepatitis A virus, hepatitis C virus and human parainfluenza virus infection and ENO1 regulates Sendai virus and dengue virus infection." (PMID 32917235, 2020). "GAPDH and DENV2 NS3 were colocalized in hepatic tissue from the fatal dengue case, as observed in the merged image of numerous Kupffer cells and hepatocytes." (PMID 30804377, 2019). "In the present study best endogenous gene among COX, ACTB, GAPDH, HMBS, HPRT and B2M during dengue fever." (PMID 30071880, 2018). "Moreover, we observed an intense colocalization between the GAPDH and NS3 proteins in DENV2-infected Huh7.5.1 cells, in NS3-transfected BHK-21 cells and in hepatic tissue from a fatal dengue case." (PMID 30804377, 2019). "Taken together, these results suggest that the human GAPDH-DENV NS3 interaction is involved in hepatic metabolic alterations, which may contribute to the appearance of steatosis in dengue-infected patients." (PMID 30804377, 2019). "In addition, our finding that GAPDH and DENV3 NS3 colocalize extensively in regions containing hepatocytes and Kupffer cells in the liver tissue of a fatal dengue case supports our hypothesis regarding the involvement of NS3 and GAPDH in viral replication." (PMID 30804377, 2019).
epilepsy (4 papers, 2012 to 2019). A brain disorder characterized by episodes of abnormally increased neuronal discharge resulting in transient episodes of sensory or motor neurological dysfunction, or psychic dysfunction. "Increase of epilepsy was found in patients positive for the antiphospholipid antibodies; however, patients with increased anti-GAPDH showed significant decreased incidence of epilepsy." (PMID 31049359, 2019). "First, we performed Western blotting to investigate GHRH expression levels in the cortices of patients with epilepsy (n = 22) and controls (n = 12); GAPDH expression was assessed as an internal loading control and was present as a 36 kDa band." (PMID 29273763, 2017). "Elevated serum anti-GAPDH was correlated with increased SLEDAI-2K (P = 0.017), ESR, IgG, and IgM and associated with increased intracranial pressure and incidence of cerebrovascular lesions, but it was protective for seizure disorder incidence." (PMID 31049359, 2019). "GAPDH levels were not significantly different in both tissues studied between CTRL and epilepsy groups." (PMID 31426844, 2019).
glaucoma (4 papers, 2015 to 2021). Increased pressure in the eyeball due to obstruction of the outflow of aqueous humor. "The first confirmed that in 10 water-glaucoma eyes the pERK/GAPDH ratio was elevated compared to controls with a ratio of 1.39, nearly twice the ratio for losartan-glaucoma." (PMID 26505191, 2015). "In GAPDH normalized Western blots, we found elevated ASAH1 and ASAH2 levels in glaucoma." (PMID 31022733, 2019).
hyperlipidemia (4 papers, 2022 to 2025). "Decreased glyceraldehyde 3-phosphate dehydrogenase activity has been observed in individuals with hyperlipidemia, resulting in enhanced uric acid synthesis." (PMID 36904083, 2023).
infertile (4 papers, 2021 to 2025). "The Ct values for GAPDH showed stable amplification across samples, ranging from 11.12 to 13.79 in the infertile male group and 11.12 to 13.36 in the control group, confirming its suitability as a reference gene for mitochondrial DNA copy number estimation." (PMID 41465075, 2025). "A number of mouse strains with KOs of sperm-specific metabolic enzymes (phosphoglycerate Kinase 2, glyceraldehyde 3-phosphate dehydrogenase, and lactate dehydrogenase C) display sperm motility defects which correlate to male-specific infertility, but in vivo migration has not been studied." (PMID 37152282, 2023). "So far, dwarfism and infertility have occurred in GAPDHC mutants due to changes in glycolysis and crab cycle intermediates, and decreased GAPDH activity." (PMID 39596534, 2024). "Antibodies against ENO1, ALDOA, GAPDH, and ODF1 were also detected in human semen from infertile men." (PMID 34576131, 2021).
injury (4 papers, 2008 to 2020). Damage inflicted on the body as the direct or indirect result of an external force, with or without disruption of structural continuity. "Earlier published data also demonstrated that GAPDH and 18S displayed variable expression levels in models of hepatitis C virus infections and in patients with an alcohol-induced liver injury." (PMID 32245194, 2020). "This work suggests that Oligreen cDNA measurements, 18S rRNA and GAPDH or a combination of them may be used to efficiently normalize qRT-PCR gene expression in mouse brain trauma injury, and that β-actin and β-microtubulin should be avoided." (PMID 18611280, 2008).
ischemic stroke (4 papers, 2014 to 2022). A stroke disorder caused by obstruction of blood flow to the brain, due to thrombotic (local blood clot formation) or embolic (due to a blood clot or other material traveling from another site) event. "Although this gene is widely used as a reference gene for evaluating inflammatory responses after ischemic stroke in mice, it is indicated that hypoxia upregulates GAPDH mRNA expression, which could have influenced the interpretation of the data." (PMID 36117859, 2022). "Based on a survey of the literature, the expression levels of the six candidate reference genes that are most commonly used for in vivo and in vitro ischemic stroke models, including HPRT, β-actin, 18S, GAPDH, Sdha and cyclophilin, were evaluated by RT-qPCR." (PMID 29390963, 2018).
meningioma (4 papers, 2011 to 2026). A generally slow growing tumor attached to the dura mater. "CONCLUSION: Cellular senescence-associated genes GAPDH, CCND1, and HBEGF show associations with M2 macrophage polarization and inflammatory cytokine secretion in meningioma." (PMID 41840566, 2026). "Established housekeeping genes in meningioma RT-qPCR experiments are genes such as glyceraldehyde-3-phosphate dehydrogenase (GAPDH) and β-Actin (ACTB) as well as ribosomal RNA (18S rRNA) and TATA binding box protein (TBP)." (PMID 21806841, 2011). "So far various reference genes (GAPDH, ACTB, S18, TBP) were used in qPCR experiments in meningiomas, although GAPDH was mainly used for normalizations." (PMID 21806841, 2011). "Eight highest ranked reference genes (CASC3, EIF2B1, IPO8, MRPL19, PGK1, POP4, PPIA, and RPL37A) plus GAPDH and ACTB were then analyzed in 35 meningiomas, arachnoidea, dura mater and normal brain." (PMID 21806841, 2011). "Those genes plus GAPDH and ACTB were compared in an increased number of meningiomas and control tissues." (PMID 21806841, 2011). "Finally, in vitro gene knockdown experiments were performed to validate the functional roles of GAPDH, CCND1, and HBEGF in meningioma and M2 macrophage polarization." (PMID 41840566, 2026). "Further analysis of FGF3 mRNA in meningioma tissues revealed that five out of six samples with KLF4K409Q (M-030, M-048, M-066, M-068, and M-070) expressed FGF3 mRNA (5.2, 21.4, 83.3, 9.8, and 298.4 copies per 106 copies of GAPDH mRNA, respectively)." (PMID 35996584, 2022). "However GAPDH and ACTB as the most used reference genes in meningioma qPCR experiments were further analyzed." (PMID 21806841, 2011). "Additionally results from the current study indicate that widely used GAPDH and ACTB are both inappropriate reference genes for meningiomas." (PMID 21806841, 2011). "Additionally the most used reference genes in meningioma qPCR experiments ACTB and GAPDH were also chosen although being only ranked in fifteenth respectively eighteens place and being considered inconsistent with a standard deviation (SD) higher than 1 by Bestkeeper-1." (PMID 21806841, 2011). "Without exception, all meningioma samples express high levels of KLF4 mRNA isoform 2, varying from 0.1 to 4.4 copies per one copy of GAPDH mRNA." (PMID 35996584, 2022).
osteoporosis (4 papers, 2015 to 2023). A condition of reduced bone mass, with decreased cortical thickness and a decrease in the number and size of the trabeculae of cancellous bone (but normal chemical composition), resulting in increased fracture incidence. "Despite OVX with deficient diet, glucocorticoid proved to be the most suitable osteoporosis model in sheep, and it was recommended to test B2M, GAPDH, RPL19, and YWHAZ gene expression that represented standard reference genes for a relative quantification of transcriptional activity of ovine bone." (PMID 36012173, 2022). "In addition, target interaction network analysis by network-based visual analysis (miRNet) showed that five genes (GAPDH, PLOD1, LMNA, WDR1, and P4HB) with five miRNAs (hsa-let-7a/b-5p, hsa-let-7b-5p, hsa-mir-16-5p, hsa-mir-18a-5p, and hsa-mir-192-5p) were associated with osteoporosis by DisGeNET." (PMID 38132172, 2023). "Based on our data we recommend testing of B2M, GAPDH, RPL19, and YWHAZ for relative quantification of gene expression studies in ovine bone which it is a robust bio-medical model for evaluating bone-substituents in osteoporosis." (PMID 29258442, 2017).
parasitic diseases (4 papers, 2016 to 2025). "Recently, GAPDH has also been proposed as a suitable vaccine candidate for protection against parasitic diseases." (PMID 39963139, 2025). "Several studies have shown that GAPDH presented in excretory/secretory products of Schistosoma japonicum and can stimulate a short-lived antibody response in hosts, suggesting that GAPDH may be useful for serological diagnosis of parasitic diseases." (PMID 29068407, 2017). "However, it has been reported that GAPDH can be recruited on the cell surface and secreted via a non-classical secretion mechanism, and therefore it is a suitable vaccine candidate for protection against bacterial and parasitic diseases." (PMID 32765437, 2020).
pneumonia (4 papers, 2019 to 2023). An acute, acute and chronic, or chronic inflammation focally or diffusely affecting the lung parenchyma, caused by an infection in one or both of the lungs (by bacteria, viruses, fungi, or mycoplasma.). "Glyceraldehyde 3‐phosphate dehydrogenase (GAPDH; degree = 13, closeness centrality = 0.54), Nucleoside diphosphate kinase B (NME2; degree = 6, closeness centrality = 0.44) and Cofilin‐1 (CFL1; degree = 6, closeness centrality = 0.42) were the three hub proteins of the pneumonia‐specific PPI network." (PMID 30761252, 2019).
psoriasis (4 papers, 2020 to 2024). An autoimmune condition characterized by red, well-delineated plaques with silvery scales that are usually on the extensor surfaces and scalp. "Dimethyl fumarate (DMF) is used in the treatment of MS and psoriasis, and its metabolites (monomethyl fumarate) succinate the glycolytic enzyme glyceraldehyde-3-phosphate dehydrogenase (GAPDH), resulting in decreasing glycolysis and increasing OXPHOS." (PMID 35626700, 2022). "DMF, an incompletely understood immunomodulatory drug used to treat psoriasis and MS, was recently shown to produce anti‐inflammatory effects through inhibition of GAPDH and aerobic glycolysis, providing proof of concept that targeting glycolysis is a viable strategy for treating human disease." (PMID 32105390, 2020).
sarcoma (4 papers, 2016 to 2023). A usually aggressive malignant neoplasm of the soft tissue or bone. "(3B) In CSC and native cells from sarcoma, the NormFinder software identified GAPDH, YWHAZ and 18S rRNA as the most stable genes, instead G6PD, RPL13a and B2M were the less stable." (PMID 26894994, 2016). "The most stable HKG for the CSC and native cells obtained only from sarcoma were GAPDH and YWHAZ, whereas for carcinoma we identified PPIA, HMBS or RPL13a." (PMID 26894994, 2016). "We analyzed the expression of the stemness genes c-Myc, KLF4, Nanog, and OCT3/4 that were previously normalized to ACTB, with the identified top-ranking HKG for CSC and native cells, in sarcoma and carcinoma, respectively (GAPDH and YWHAZ for sarcoma, and PPIA and HMBS for carcinoma)." (PMID 26894994, 2016). "Notably, YWHAZ and GAPDH were revealed as the most stable HKG in all the pH conditions, confirming its suitability as a HKG to gene normalization of sarcoma cells." (PMID 30261649, 2018).
squamous cell carcinoma (4 papers, 2018 to 2024). A carcinoma arising from squamous epithelial cells. "ΔNp63α, a splice isoform of TP63, induces the expression of GAPDH in squamous cell carcinoma when phosphorylated." (PMID 35886000, 2022). "In contrast, only three genes (KRT8, KRT18, and GAPDH) correlate with significantly reduced OS of squamous cell carcinoma patients (N = 525), mirroring the histological classification of the murine KM tumours as adenocarcinoma." (PMID 31032816, 2019).
thyroid cancer (4 papers, 2001 to 2023). "In a comprehensive investigation of thyroid cancer subtype, we discovered that GAPDH was significantly influenced by the aggressiveness of thyroid tumor subtypes." (PMID 35778437, 2022). "Several studies on primary thyroid cancers and thyroid cancer-derived cell lines have employed GAPDH as a reliable internal reference gene because the transcription of GAPDH is stable in most experimental conditions." (PMID 31645594, 2019). "To evaluate this usefulness, we measured TG mRNA in the peripheral blood of patients diagnosed with thyroid carcinoma after total thyroidectomy by real-time quantitative RT-PCR using glyceraldehyde-3-phosphate dehydrogenase (GAPDH) mRNA as an internal control." (PMID 11437410, 2001).
type 1 diabetes (4 papers, 2017 to 2025). "Our previous study on type 1 diabetes demonstrated that SUMOylation positively regulates key metabolic enzymes, including Glyceraldehyde-3-phosphate dehydrogenase (GAPDH), citrate synthase, and transketolase-like protein-1 (TKTL1), within the Krebs cycle." (PMID 37947589, 2023). "BCG-induced activation of the glycolytic enzyme GAPDH may relate to the conversion of anaerobic to aerobic glycolysis demonstrated in type 1 diabetic patients vaccinated with BCG that showed glycemic relief only 3 years after vaccination." (PMID 40699791, 2025). "The higher the enzymatic activity, the lower the level of MGO, and this relationship was also seen between red blood cell GAPDH activities and plasma MGO levels normalized to blood glucose in type 1 diabetic patients." (PMID 35624868, 2022).
asthenozoospermia (3 papers, 2021 to 2023). "The protein expressions of GRIM-19 in sperms of the asthenozoospermia group were significantly lower than that of the normal group as well (GRIM-19/GAPDH: 0.827 ± 0.063 vs 0.458 ± 0.033; P < 0.001)." (PMID 36813832, 2023). "Western blotting analysis showed that the expression of protein of GRIM-19 in the spermatozoa of patients with asthenozoospermia was also significantly lower than in the normal control group (GRIM-19/GAPDH: 0.827 ± 0.063 vs 0.458 ± 0.033; P < 0.001)." (PMID 36813832, 2023).
Autoimmunity (3 papers, 2017 to 2022). The occurrence of an immune reaction against the organism's own cells or tissues. "The numerous studies showed that GAPDH plays an essential role in the induction of autoimmunity, but how anti-GAPDH immune response originated in various diseases is still unknown." (PMID 28503176, 2017). "Furthermore, CD GAPDH specific epitopes may induce antibodies directly against self-antigens leading to autoimmunity which is why it should not be used in a vaccine as a whole protein." (PMID 30224677, 2018).
B cell lymphoma (3 papers, 2022 to 2025). "In addition, BTG1 is an anti-proliferative gene that is frequently mutated in B cell lymphomas, while GAPDH participates in glycolysis which displays greater activity during inflammation." (PMID 41208955, 2025). "Lastly, the expression levels of glyceraldehyde-3-phosphate dehydrogenase (GAPDH), cleaved caspase-9, cytochrome C (Cyt-C), B cell lymphoma/leukemia-2 (Bcl-2), B cell lymphoma/leukemia-2 associated X (Bax), AKT, p-AKT, PI3K, and p-PI3K were analyzed utilizing western blotting." (PMID 35414825, 2022). "Silencing of Glyceraldehyde-3-phosphate dehydrogenase (GAPDH), a critical enzyme regulating glycolysis, in Eμ-Myc-GAPDHhigh cells isolated from mouse primary B lymphomas (used as a model of aggressive non-Hodgkin B-cell lymphomas) led to a metabolic switch towards glutamine and OxPhos metabolism." (PMID 39941763, 2025).
cholesteatoma (3 papers, 2020 to 2023). A pathologic process characterized by the proliferation of keratinizing squamous epithelium resulting in the accumulation of keratin and cells in the middle ear and/or mastoid. "The expression of INHBA mRNA normalized relative to glyceraldehyde-3-phosphate dehydrogenase (GAPDH) mRNA was significantly higher in cholesteatoma fibroblasts than in control dermal fibroblasts." (PMID 37537159, 2023). "The level of RANKL expression normalized relative to that of GAPDH was significantly higher in cholesteatoma than in the control dermis." (PMID 37537159, 2023). "A considerable variation was seen in expression levels between the different candidate reference genes, with mean Ct-values ranging from 17.74 for GAPDH in the mucosal biopsies from the TC in cholesteatoma patients to 27.70 for CANX in the MA from healthy controls." (PMID 32915926, 2020). "For cholesteatoma tissue, the ME-CSCs and ME-CFs showed a similar distribution of TLR4 expression between 1 and 0.1% relative to GAPDH." (PMID 33627146, 2021). "For TC samples from healthy controls and cholesteatoma patients, all three programs ranked ACTB and GAPDH among the most stable genes." (PMID 32915926, 2020). "Validation of reference genes using c-MYC expression confirmed the suitability of ACTB and GAPDH as reference genes and showed an upregulation of c-MYC in middle ear mucosa during cholesteatoma." (PMID 32915926, 2020).
colon adenocarcinoma (3 papers, 2008 to 2016). "However, colon adenocarcinoma cell lines, as demonstrated here by rather low intergroup variability both when assessed combined and individually, do not respond to alterations in serum availability by substantial changes in GAPDH levels." (PMID 27339468, 2016).